DVL3 (dishevelled segment polarity protein 3)
Description:
Involved in the signal transduction pathway mediated by multiple Wnt genes.
Synonyms: KIAA0208; DRS3
Tractability: Small molecule: a structure with a bound ligand is known. Antibody: the Human Protein Atlas places it where antibodies can reach. PROTAC: UniProt records ubiquitination sites on it; ubiquitination databases record sites on it; its protein half-life has been measured.
Gene: Protein-coding gene on chromosome 3 (184,155,159 to 184,173,614, forward strand). Ensembl gene ENSG00000161202.
Subcellular location: Cytoplasm
Subcellular location (Human Protein Atlas): Basal body; Midbody ring; Centrosome; Golgi apparatus; Intermediate filaments; Plasma membrane
Pathways (Reactome):
Signal Transduction: Degradation of DVL; Disassembly of the destruction complex and recruitment of AXIN to the membrane; Negative regulation of TCF-dependent signaling by DVL-interacting proteins; PCP/CE pathway; RHO GTPases Activate Formins; TCF dependent signaling in response to WNT; WNT mediated activation of DVL
Disease: WNT5:FZD7-mediated leishmania damping
Gene Ontology:
Molecular function: beta-catenin binding; frizzled binding; protease binding; protein binding; signaling receptor binding; small GTPase binding; protein-macromolecule adaptor activity
Biological process: canonical Wnt signaling pathway; non-canonical Wnt signaling pathway; positive regulation of DNA-templated transcription; positive regulation of JNK cascade; positive regulation of transcription by RNA polymerase II; protein stabilization; regulation of protein localization; small GTPase-mediated signal transduction; Wnt signaling pathway, planar cell polarity pathway; positive regulation of neuron projection arborization; regulation of actin cytoskeleton organization; intracellular signal transduction; Wnt signaling pathway
Cellular component: chromatin; cytosol; cytoplasm; glutamatergic synapse; synapse; Wnt signalosome
Genetic constraint (gnomAD): Loss-of-function variants: 27 observed, 69.45 expected, observed/expected ratio (o/e) 0.39, 90% interval 0.29 to 0.54. The upper end of that interval is the gene's LOEUF score, 0.54, which puts it in group 2 of 6, group 1 being the genes least tolerant of losing a copy. Missense variants: 819 observed, 1,037.4 expected, observed/expected ratio (o/e) 0.79, 90% interval 0.75 to 0.84. Synonymous variants: 369 observed, 400.28 expected, observed/expected ratio (o/e) 0.92, 90% interval 0.85 to 1.
Homologues: Orthologues: chimpanzee DVL3 (100% identical), macaque DVL3 (99% identical), pig DVL3 (99% identical), dog DVL3 (98% identical), mouse Dvl3 (98% identical), guinea pig DVL3 (96% identical), rat Dvl3 (93% identical), rabbit DVL3 (91% identical), tropical clawed frog dvl3 (86% identical), zebrafish dvl3b (78% identical), zebrafish dvl3a (69% identical), Drosophila melanogaster dsh (41% identical), and 3 more. Paralogues in human: DVL2 (70% identical), DVL1 (65% identical), DIXDC1 (14% identical).
Diseases named in the same sentence as DVL3 in open-access papers:
DVL3 is named in the same sentence as 89 diseases in open-access papers, as found by Europe PMC text mining. Sharing a sentence is not in itself a finding about the gene and the disease. The quoted sentences say what the papers report.
breast cancer (22 papers, 2007 to 2025). A primary or metastatic malignant neoplasm involving the breast. "DVL3 is observed to be implicated in the breast cancer pathways and negatively regulated by miR-1275." (PMID 33910530, 2021). "DVL3 is implicated in the breast cancer pathways and negatively controlled by miR-1275." (PMID 33910530, 2021). "The results revealed that the expression of key proteins associated with the β-catenin signaling pathway, such as DVL3, NAKED2, and β-catenin, consistently decreased in a time-dependent manner following BmK-M9 treatment in breast cancer cells." (PMID 40080350, 2025). "Disheveled segment polarity protein 3 (DVL3), an upstream modulator of the Wnt/β-catenin signaling pathway, significantly promotes breast cancer progression." (PMID 36677797, 2023). "Our group has recently published a comprehensive DVL ChIP Seq study to understand the genome-wide binding patterns of DVL-3 in human breast cancer models." (PMID 34733415, 2021). "AMPK activators inhibit breast cancer cell proliferation by inhibiting DVL3-promoted Wnt/β-catenin signaling pathway activity." (PMID 32461838, 2020). "Upregulated Dvl3 was also recently investigated as a biomarker for the recurrence of prostate cancer, while its downregulation sensitizes prostate and breast cancer cells to insulin-like growth factor 1 (IGF1)." (PMID 31126091, 2019). "We first examined the transcript abundance of DVL homologs from the 1093 breast cancer patients and found that DVL3 transcripts were most abundant in clinical samples." (PMID 29895829, 2018). "DVL1 and DVL3 were consistently expressed at relatively uniform levels in all the breast cancer cell lines, whereas DVL2 was expressed in a more differential manner." (PMID 17897439, 2007). "Given our previous findings demonstrating that DVL-1 plays a critical role in regulating a TIAM1-Rac1 signaling axis in MDA-MB-231 cells, and endogenous DVL-3 co-precipitates with SIRT1 in breast cancer cells, we were interested in exploring these two family members in particular." (PMID 30479694, 2018). "Interestingly, DVL-1 and DVL-3 were present at different levels in both nuclear and cytoplasmic fractions in multiple breast cancer lines." (PMID 30479694, 2018). "Since it is known that ROR1/2 signaling, especially after stimulation with Wnt5a, requires Dvl for signal transduction, we aimed to analyze which of the Dvl proteins (Dvl1, Dvl2 or Dvl3) might be a good marker for active ROR signaling in breast cancer." (PMID 26862065, 2016). "Whether Dvl1 and Dvl3, homologs of Dvl2, induce the migration of breast cancer cells needs to be further studied." (PMID 22655072, 2012). "In breast cancer, AMPK activators suppress breast-cancer-cell growth by inhibiting DVL3-facilitated Wnt/y can be useful for chemn by targetin." (PMID 34572839, 2021). "Upregulation and increased levels of disheveled segment polarity protein 3 (DVL3) and β-catenin were found in the MCF7, MDA-MB-231, and T47D breast cancer cells when compared to healthy MCF10A breast cells." (PMID 32883003, 2020). "As shown in three independent experiments in a panel of breast cancer cell lines, we found that both DVL-1 and DVL-3 bind the I.1 promoter in MCF7, MDA-MB-231 and BT-549 while only DVL-3 binds to I.1 in MDA-MB-468." (PMID 30479694, 2018). "Based on the comprehensive ChIP Seq studies that we performed for DVL-1 and DVL-3 in breast cancer cell lines, we observed that DVL proteins target non-canonical genes." (PMID 34659647, 2021). "Our gene expression data also support a role in ST-3 activation of Wnt-signalling components, such as FZD7 and DVL3, which is in line with the activation of the Wnt pathway by ST-1/MMP-3 via E-cadherin cleavage, resulting in EMT and thus enhanced invasive properties of mammary tumour cells." (PMID 17233884, 2007).
lung carcinoma (16 papers, 2011 to 2024). "High DVL3 expression is associated with poor prognosis in patients with lung cancer." (PMID 35273597, 2022). "Similarly, Dvl3 has been implicated in p65 nuclear translocation of p65 via a p38-dependent activation mechanism in lung cancer cells." (PMID 31510045, 2019). "DVL1 affects the biological behavior of lung carcinoma cells primarily through the β-catenin (canonical Wnt) pathway, while DVL3 acts primarily through the p38 and JNK pathways." (PMID 36035311, 2022). "The authors report on downregulation of DVL1 RNA in glioblastoma and upregulation of DVL3 RNA in lung cancer." (PMID 30468298, 2019). "Our investigations of DVL1 and DVL3 protein levels showed overexpression in brain metastasis of lung cancers." (PMID 25358879, 2014). "In primary lung cancer DVL3 is overexpressed in non small cell lung cancer, implying that these events upstream of beta-catenin are critical for activation of Wnt signaling." (PMID 25358879, 2014). "Our results on DVL1, DVL3, beta-catenin and E-cadherin bring novel insights on the Wnt signaling role in brain metastases that originated from primary lung carcinomas." (PMID 24933634, 2014). "DVL-3 is a member of the human dishevelled family, located on chromosome 3q27, is abnormally expressed in nonsmall cell lung cancer, and affect lung cancer cell invasiveness and metastasis." (PMID 22461838, 2012). "On the other hand, the disheveled segment polarity protein 3 (encoded by DVL3), a key mediator of Wnt/β-catenin signaling, which was significantly upregulated in the advanced stage EEC tumors, has been shown to be a driver of lung cancer metastases." (PMID 29731976, 2018). "Therefore, DVL-3 mRNA and δ-catenin mRNA are sensitive molecular markers for the diagnosis of lung cancer." (PMID 22461838, 2012). "DVL-3 belongs to Dishevelled (Dvl) family proteins which are cytoplasmic mediators of the Wnt/beta-catenin signaling pathway and have recently been proved to be overexpressed in nonsmall cell lung cancer (NSCLC), especially in adenocarcinomas." (PMID 22461838, 2012). "In lung cancer, DVLs was reportedly to activate Wnt pathway and brain metastasis had increased expression of DVL1 and DVL3, which are potential targets of hsa_circ_0002360 and hsa_circ_0009117, respectively." (PMID 35123506, 2022). "In the present study, 31 brain metastases that originated from primary lung carcinomas were analyzed regarding over expression of Dishevelled-1 (DVL1), Dishevelled-3 (DVL3), E-cadherin (CDH1) and beta-catenin (CTNNB1)." (PMID 24933634, 2014). "The work presented in this paper focused on the analysis of different expression levels of Dishevelled-1 (DVL1), Dishevelled-3 (DVL3), beta-catenin (CTNNB1) and E-cadherin (CDH1) in brain metastases that originated from primary lung carcinomas." (PMID 24933634, 2014). "For example, differential expression of several WNT components including WNT1, WNT2, WNT7A, DVL3, β-CATENIN and APC, have been reported in normal lung tissues and lung cancers, particularly in NSCLC (non-small cell lung cancer)." (PMID 22846383, 2012). "Next, we performed quantitative PCR on three Wnt pathway genes (FZD6, DVL3, WNT5A) in a commercial panel of 40 lung cancer samples (Origene; Rockville, MD)." (PMID 22016777, 2011).
prostate carcinoma (10 papers, 2013 to 2024). A carcinoma that arises from epithelial cells of the prostate gland. "In support, it has recently been shown that DVL3 increases the proliferation and migration of prostate cancer cells via the Toll-like receptor 4 (TLR4) pathway." (PMID 39596188, 2024). "In prostate cancer, DVL1/2/3 are rarely mutated (<1%), however DVL3 is amplified in up to 2.2% of primary cases, and as many as 8.8% of metastatic cases." (PMID 35204808, 2022). "CRIPTO has also been proposed to regulate EMT and stemness via stabilizing the WNT pathway regulator disheveled segment polarity protein 3 (DVL3) in several tumor types including prostate cancer and hepatocellular carcinoma." (PMID 34576327, 2021). "This is not surprising, since many studies have revealed the role of DVL3 in the pathogenesis and prognosis of different types of tumors, including colorectal cancer, liver cancer, lung adenocarcinoma, pancreatic adenocarcinoma, and prostate cancer." (PMID 39596188, 2024). "Interestingly, DVL1 amplification and over-expression were observed in breast and prostate cancers respectively, while DVL3 mRNA was significantly increased in pleural effusions from patients with lung cancer and was over-expressed in NSCLC." (PMID 35204808, 2022). "ASPM binds to disheveled segment polarity protein 3 (DVL-3), a key upstream regulator of canonical Wnt signaling, and prevents it from being degraded by the proteasome, thereby strengthening protein stability and enhancing Wnt-induced β-catenin transcriptional activity in prostate cancer cells." (PMID 36969009, 2023). "Additionally, DVL3 acts as a modulator of resistance to IGFIR inhibition in breast and prostate cancer cells." (PMID 36614043, 2022).
Robinow syndrome (8 papers, 2018 to 2025). Robinow syndrome (RS) is a rare genetic syndrome characterized by limb shortening and abnormalities of the head, face and external genitalia. "Mutations in genes from WNT pathways, including ROR2, FZD2, WNT5A, DVL1, and DVL3, have all been found to cause Robinow syndrome in humans." (PMID 30521570, 2018). "In our cohort, BG45 had a probable diagnosis of Robinow syndrome caused by DVL3." (PMID 40796658, 2025). "The mutations of APC may cause Gardner syndrome, besides gene mutations of Ror2, Dvl1, Dvl3 and Wnt5a are associated with Robinow syndrome." (PMID 37194731, 2023). "Importantly, analogous frameshift mutations in the human DVL1 and DVL3 genes cause Robinow syndrome, a congenital disorder characterized by similar craniofacial, limb and vertebral malformations." (PMID 30521570, 2018). "Among the genetic causes associated with these phenotypes, pathogenic variants in DVL1/DVL3 and WNT5A (all (i.a.)for Robinow syndrome) and TCTN3 (orofaciodigital syndrome 4) have been identified." (PMID 34629465, 2022). "Similar clinical signs are seen in Robinow syndrome in humans, a hereditary disorder caused by gene defects in the Wnt signaling pathway, including DVL1, DVL3, ROR2, WNT5A, FZD2 and NXN." (PMID 33599851, 2021). "The location of the truncation of the protein is remarkably similar to the effect of mutations within the other Dishevelled family members, DVL1 and DVL3, that lead to Robinow syndrome in people." (PMID 30521570, 2018). "Analogous truncations in the same regions of human DVL1 and DVL3 proteins result in Robinow syndrome in humans." (PMID 30521570, 2018). "Of these, receptor tyrosine kinase-like orphan receptor 2 (ROR2) and nucleoredoxin (NXN) are linked to autosomal recessive Robinow syndrome, whereas dishevelled genes (DVL1, DVL2 and DVL3), WNT5A and Frizzled2 (FZD2) have autosomal dominant inheritance (autosomal dominant Robinow syndrome)." (PMID 38967226, 2024). "In addition to the bulldog DVL2 frameshift mutation, human mutations causing Robinow syndrome have been identified in WNT5A, ROR2, FZD2, DVL1, and DVL3, which are all major components of the WNT5A-ROR pathway." (PMID 30521570, 2018). "Most of the genes implicated in the pathogenesis of Robinow syndrome function in the non-canonical c-Jun N-terminal kinase (JNK)/planar cell polarity (PCP) pathway except for FZD2, DVL1, DVL2 and DVL3, which also operate in the canonical/β-catenin-mediated WNT pathway." (PMID 38967226, 2024).
cervical cancer (7 papers, 2013 to 2023). A primary or metastatic malignant neoplasm involving the cervix. "By western blot and immunohistochemical analyses, we demonstrated that DVL3 was frequently upregulated and significantly associated with elevated β-catenin (P = 0.009) and CyclinD1 (P = 0.009) expressions in cervical cancer." (PMID 23301094, 2013). "Kwan and coworkers reported a significant link between DVL3 upregulation and increased Wnt/β-catenin activity in cervical cancer." (PMID 37681914, 2023). "Dvl3, as a multivalent scaffold with several well-known domains, is significantly upregulated in cervical cancer and participates in cervical cancer oncogenesis via Wnt/β-catenin activation." (PMID 35965516, 2022). "Metformin inhibits the growth of cervical cancer cells by impairing DVL3 protein synthesis or partially promoting the proteasomal degradation of DVL3." (PMID 34067321, 2021). "Enforced expression of DVL3 elevated β-catenin and augmented cervical cancer cell growth, verifying that DVL3-mediated Wnt/β-catenin activation is involved in cervical cancer oncogenesis." (PMID 23301094, 2013). "More importantly, we are the first to provide evidence that AMPK activators inhibit cervical cancer cell growth through impairing DVL3-mediated Wnt/β-catenin signaling in cervical cancer cells." (PMID 23301094, 2013). "Here we show that AMPK activators impair cervical cancer cell growth through the reduction of DVL3, a positive regulator in Wnt/β-catenin signaling and an oncogenic player in cervical cancer tumorigenesis." (PMID 23301094, 2013). "Taken together, these findings indicate that the increased expression of DVL3 is correlated with β-catenin which is involved in cervical cancer development." (PMID 23301094, 2013). "Clinicopathological correlation of DVL3 expression in cervical cancer tissue array (CX1021) (Pantomics, CA, USA)." (PMID 23301094, 2013). "In conclusion, we revealed the oncogenic role of DVL3 in augmented Wnt/β-catenin signaling activity in cervical cancer." (PMID 23301094, 2013). "The immunoreactivity of DVL3 was only observed in the cytoplasm whereas β-catenin localized in both nuclei and cytoplasmic regions of both normal and cervical cancer cells." (PMID 23301094, 2013). "Our previous research has shown that pharmaceutical AMPK activators are able to repress cervical cancer cell growth through targeting DVL3 in the Wnt/β-catenin signaling pathway." (PMID 23819460, 2013). "Upon treatment of Rapamycin, DVL3 was reduced in cervical cancer cell lines (C33A, C41, CaSki, HeLa and SiHa) in a dose-dependent manner." (PMID 23301094, 2013). "Collectively, these findings indicate that DVL3 is the major isoform of DVLs frequently up-regulated in cervical cancers cells." (PMID 23301094, 2013). "In this study, we showed that DVL3 was significantly upregulated and was correlated with Wnt/β-catenin activity in cervical cancer." (PMID 23301094, 2013). "Collectively, these findings suggest that DVL3 enhances Wnt/β-catenin signaling activity and promotes the proliferation of cervical cancer cells." (PMID 23301094, 2013). "More importantly, we addressed the potential use of AMPK activators in reducing DVL3 and hence inhibiting the cervical cancer cell growth." (PMID 23301094, 2013). "In this study, we have shown that DVL3 was aberrantly over-expressed and significantly correlated with increased β-catenin in cervical cancer." (PMID 23301094, 2013). "To study the significance of DVL3 and β-catenin in cervical cancer, we examined the expressions of DVL3 and β-catenin on a cervical cancer tissue array (CX1021) using immunohistochemical (IHC) analysis." (PMID 23301094, 2013). "AICAR treatment resulted in significant reduction of DVL3 levels in three cervical cancer cell lines." (PMID 23301094, 2013).